RBBP4 (RB binding protein 4, chromatin remodeling factor)
Description:
Core histone-binding subunit that may target chromatin assembly factors, chromatin remodeling factors and histone deacetylases to their histone substrates in a manner that is regulated by nucleosomal DNA. Component of the chromatin assembly factor 1 (CAF-1) complex, which is required for chromatin assembly following DNA replication and DNA repair. Component of the core histone deacetylase (HDAC) complex, which promotes histone deacetylation and consequent transcriptional repression. Component of the nucleosome remodeling and histone deacetylase complex (the NuRD complex), which promotes transcriptional repression by histone deacetylation and nucleosome remodeling. Component of the PRC2 complex, which promotes repression of homeotic genes during development. Component of the NURF (nucleosome remodeling factor) complex.
Synonyms: RBAP48; NURF55; lin-53
Tractability: Small molecule: a structure with a bound ligand is known; a high-quality ligand is known; it has a high-quality binding pocket. PROTAC: UniProt records ubiquitination sites on it; ubiquitination databases record sites on it; its protein half-life has been measured; a small molecule that binds it is known.
Target class: Other nuclear protein
Gene: Protein-coding gene on chromosome 1 (32,651,142 to 32,686,211, forward strand). Ensembl gene ENSG00000162521.
Subcellular location: Nucleus; Chromosome, telomere
Subcellular location (Human Protein Atlas): Nucleoplasm
Pathways (Reactome):
Cell Cycle: Cyclin A:Cdk2-associated events at S phase entry; Cyclin E associated events during G1/S transition; Deposition of new CENPA-containing nucleosomes at the centromere; G0 and Early G1; G1/S-Specific Transcription; Polo-like kinase mediated events; Transcription of E2F targets under negative control by DREAM complex; Transcription of E2F targets under negative control by p107 (RBL1) and p130 (RBL2) in complex with HDAC1
Gene expression (Transcription): ERCC6 (CSB) and EHMT2 (G9a) positively regulate rRNA expression; PRC2 methylates histones and DNA; RNA Polymerase I Transcription Initiation; Regulation of endogenous retroelements by KRAB-ZFP proteins; Regulation of endogenous retroelements by Piwi-interacting RNAs (piRNAs); Transcriptional Regulation by E2F6
Chromatin organization: HDACs deacetylate histones; Interaction of NuRD complexes with transcription factors; NuRD complex assembly; PKMTs methylate histone lysines
Developmental Biology: Activation of anterior HOX genes in hindbrain development during early embryogenesis; Differentiation of naive CD4+ T cells to T helper 2 cells (Th2 cells); Transcriptional regulation of brown and beige adipocyte differentiation by EBF2
Disease: Defective pyroptosis; HCMV Early Events; Potential therapeutics for SARS
Cell-Cell communication: Negative Regulation of CDH1 Gene Transcription
Cellular responses to stimuli: Oxidative Stress Induced Senescence
Immune System: Regulation of PD-L1(CD274) transcription
Signal Transduction: Regulation of PTEN gene transcription
Gene Ontology:
Molecular function: ATP-dependent activity, acting on DNA; histone binding; histone deacetylase binding; nucleosomal DNA binding; protein binding; RNA polymerase II cis-regulatory region sequence-specific DNA binding
Biological process: chromatin remodeling; DNA replication-dependent chromatin assembly; regulation of DNA-templated transcription; brain development; heterochromatin formation; negative regulation of cell migration; negative regulation of cell population proliferation; negative regulation of DNA-templated transcription; negative regulation of stem cell population maintenance; negative regulation of transcription by RNA polymerase II; negative regulation of transforming growth factor beta receptor signaling pathway; positive regulation of DNA-templated transcription; positive regulation of stem cell population maintenance; positive regulation of transcription by RNA polymerase II; regulation of cell fate specification; regulation of stem cell differentiation
Cellular component: ATPase complex; CAF-1 complex; chromatin; chromosome, telomeric region; ESC/E(Z) complex; histone deacetylase complex; nucleoplasm; nucleus; NuRD complex; NURF complex; protein-containing complex; DRM complex; RNA polymerase II transcription regulator complex; Sin3-type complex
Genetic constraint (gnomAD): Loss-of-function variants: 3 observed, 53.95 expected, observed/expected ratio (o/e) 0.0556, 90% interval 0.024 to 0.14. The upper end of that interval is the gene's LOEUF score, 0.14, which puts it in group 1 of 6, group 1 being the genes least tolerant of losing a copy. Missense variants: 97 observed, 500.81 expected, observed/expected ratio (o/e) 0.19, 90% interval 0.16 to 0.23. Synonymous variants: 135 observed, 161.47 expected, observed/expected ratio (o/e) 0.84, 90% interval 0.73 to 0.96.
Homologues: Orthologues: chimpanzee RBBP4 (100% identical), dog RBBP4 (100% identical), macaque RBBP4 (100% identical), mouse Rbbp4 (100% identical), tropical clawed frog rbbp4 (99% identical), zebrafish rbbp4 (97% identical), rat Rbbp4l1 (96% identical), rabbit RBBP4 (92% identical). Paralogues in human: RBBP7 (88% identical), GEMIN5 (21% identical), GRWD1 (17% identical), WDR59 (17% identical), PEX7 (16% identical), WDR24 (14% identical), WDR73 (14% identical), WDR77 (13% identical), ERCC8 (13% identical).
Diseases named in the same sentence as RBBP4 in open-access papers:
RBBP4 is named in the same sentence as 70 diseases in open-access papers, as found by Europe PMC text mining. Sharing a sentence is not in itself a finding about the gene and the disease. The quoted sentences say what the papers report.
glioblastoma (13 papers, 2018 to 2026). The most malignant astrocytic tumor (WHO grade IV). "Previous reports have shown that miR-145 and miR-885-5p target RBBP4 to regulate non-small cell lung cancer cell proliferation 25 and glioblastoma carcinogenesis 26, respectively." (PMID 39430246, 2024). "In humans, Rbbp4‐dependent recruitment of chromatin regulators has been demonstrated in glioblastoma multiforme cell resistance to temozolomide through p300 activation of DNA repair pathway genes." (PMID 35266256, 2022). "In short, our study proved that the HOXA-AS2/miR-885-5p/RBBP4 axis influenced the growth of glioblastoma cells." (PMID 33430870, 2021). "Overall, HOXA-AS2 promoted the tumorigenesis of glioblastoma by targeting and regulating miR-885-5p to induce the expression of RBBP4." (PMID 33430870, 2021). "The CCK-8 assay results proved that si-RBBP4 inhibited the cell viability of the glioblastoma cells after a transfection period of 48 and 72 h." (PMID 33430870, 2021). "More specifically, we found that HOXA-AS2 contributed to the viability, proliferation and adhesion of glioblastoma cells, but it inhibited cell apoptosis by stimulating miR-885-5p to release RBBP4." (PMID 33430870, 2021). "RBBP4, a measurable downstream target of miR-885-5p, was found to be upregulated in glioblastoma cells, thereby enhancing the malignant phenotypes of glioblastoma cells." (PMID 33430870, 2021). "Our research revealed the influence of the HOXA-AS2/miR-885-5p/RBBP4 axis on the progression of glioblastoma carcinogenesis." (PMID 33430870, 2021). "This limitation makes it difficult to understand the impact of the HOXA-AS2/miR-885-5p/RBBP4 axis on glioblastoma progression." (PMID 33430870, 2021). "The expression of RBBP4 mRNA and protein in glioblastoma cells was upregulated in U87 and U251 cells." (PMID 33430870, 2021). "In human glioblastoma (GBM) tumor cells, knockdown of RBBP4 causes sensitization of tumor cells to temozolomide (TMZ) chemotherapy and supresses the expression of several DNA repair genes, including RAD51, a key enzyme of the homologous recombination repair pathway." (PMID 34086947, 2021). "Our study focused chiefly on the interaction and role of the HOXA-AS2/miR-885-5p/RBBP4 axis in the development of glioblastoma." (PMID 33430870, 2021). "After that, CCK-8 assay, BrdU assay, nude mice xenografting assay, western blot assay, and flow cytometry were carried out to analyze the effect of the HOXA-AS2/miR-885-5p/RBBP4 axis on glioblastoma samples." (PMID 33430870, 2021). "Experimental results showed that HOXA-AS2 and RBBP4 contributed to the tumorigenesis of glioblastoma cells." (PMID 33430870, 2021). "Consistent with observations in glioblastoma tumors, RebL1 depletion suppressed DNA repair protein Rad51 in Tetrahymena, thus underscoring the evolutionarily conserved functions of RBBP4/7 proteins." (PMID 34086947, 2021). "This indicates that cyclinD1 expression in glioblastoma cells is specified, which might be the reason why cyclinD1 expression is unaffected after RBBP4 downregulation." (PMID 40187236, 2025). "Beyond glioblastoma, the authors observed that RBBP4 knockdown significantly reduced cyclin D1 expression in hepatocellular carcinoma, colorectal cancer, and breast cancer cell lines (data not shown), further supporting the importance of RBBP4 in regulating gene expression across various tumors." (PMID 40187236, 2025). "Besides, RBBP4 disruption was found to suppress glioblastoma growth in vivo and was confirmed to be a tumor promoter in gastric cancer samples." (PMID 33430870, 2021). "HOXA-AS2 and RBBP4 were found to be overexpressed in glioblastoma." (PMID 33430870, 2021). "After analyzing the expression of RBBP4 mRNA in 33 glioblastoma tissues, we noticed that RBBP4 expression was elevated by 2.5-fold in glioblastoma tissues, and RBBP4 expression was negatively related to miR-885-5p expression in glioblastoma tissues." (PMID 33430870, 2021).
glioblastoma (continued). "To investigate whether the miR-885-5p/RBBP4 axis could regulate the tumorigenesis of glioblastoma cells, we transfected si-RBBP4, miR-885-5p inhibitor or miR-885-5p inhibitor plus si-RBBP4 into U87 and U251 cells." (PMID 33430870, 2021). "After performing bioinformatics analysis, RBBP4 was identified to be the key gene in glioblastoma." (PMID 33430870, 2021). "Overall, HOXA-AS2 promoted glioblastoma through the HOXA-AS2/miR-885-5p/RBBP4 axis." (PMID 33430870, 2021). "In zebrafish neural precursors, Rbbp4 could assist in genome maintenance through p300 activation of gene expression in DNA repair pathways, as was reported in glioblastoma cells." (PMID 29914980, 2018). "However, it is unclear whether RBBP4 plays a significant role in glioblastoma and whether it can be regulated by miRNAs." (PMID 33430870, 2021). "Hence, our study aimed to unravel the role of the HOXA-AS2/miR-885-5p/RBBP4 axis in glioblastoma." (PMID 33430870, 2021). "Moreover, si-RBBP4 could counteract the cell adhesion role of the miR-885-5p inhibitor in glioblastoma cells." (PMID 33430870, 2021). "Besides, the RBBP4 served as an oncogene to facilitate malignant phenotypes of glioblastoma cells, and it could overturn the inhibitory influence of miR-885-5p on glioblastoma cells." (PMID 33430870, 2021). "In a glioblastoma (GBM) study, knocking down RBBP4 resulted in significant tumor cell sensitization to temozolomide (TMZ) and inhibited multiple DNA repair genes." (PMID 39109577, 2024). "RBBp4 is also overexpressed in different cancer types, including TNBC, glioblastoma, hepatocellular carcinoma (HCC) and acute myeloid leukaemia." (PMID 36362083, 2022). "RBBP4 expression is altered in human glioma, and was recently shown to cooperate with the p300 (EP300) histone acetyl transferase to activate DNA repair pathway gene expression in glioblastoma cells in response to temozolomide." (PMID 29914980, 2018).
breast carcinoma (11 papers, 2018 to 2025). "Another documented ISWI subfamily member implicated in breast cancer progression is the NURF complex with BPTF and RBBP4/7 subunits." (PMID 41278204, 2025). "We confirmed these results by immunoblot analysis and showed a significant increase in the level of NuRD complex proteins in TMG treated breast cancer cells compared to controls with the exception of RBBP4." (PMID 40136647, 2025). "In TNBC, B-cell CLL/lymphoma-11A (BCL11A) is a transcription factor that contributes to maintaining the chemo-resistant breast cancer stem cell population through its interaction with RBBP4." (PMID 41278204, 2025). "In breast cancer cells, RBBP4 interacts with lncRNA LCPAT1 to activate MFAP2, whose transcription then regulates the proliferation, migration and invasion of cancer." (PMID 38028543, 2023). "Unconventionally, mutations in the WD40 repeat sequence in the RBBP4 structure also allow protein relocalization of BRCA1, a tumor suppressor protein closely associated with breast cancer, thus promoting cancer progression." (PMID 38028543, 2023). "RBBP4/7 is often highly expressed in breast cancer and exerts cancer-promoting effects through multiple pathways." (PMID 38028543, 2023). "We have shown the association of PUF-A with RbAp48/RBBP4 and DDX3 in breast cancer MDA-MB-231 cells." (PMID 34407138, 2021). "In breast cancer, RBBP4/7 are known to function as part of HDAC complexes." (PMID 41278204, 2025). "Mechanistically, LCPAT1 could recruit retinoblastoma-binding protein 4 (RBBP4) to the promoter region of microfibril-associated protein 2 (MFAP2) to induce its expression, thus contributing to breast cancer." (PMID 36613528, 2022). "Inhibition of RBBP4-BCL11A complex formation by BCL11A peptide inhibitor may decrease aldehyde dehydrogenase-positive breast cancer stem cells; hence, targeting interactions between RBBP4 and oncogenic transcription factors may provide opportunities for intervention." (PMID 41278204, 2025). "RBBP4 is involved in apoptosis in early mouse embryonic development, and NUP43 plays a crucial role in various cancers, including breast cancer and gastric cancer." (PMID 37547318, 2023). "Moreover, RBBP4/7 can bind to BCL11A, a key protein that plays a tumorigenic role in triple-negative breast cancer and breast cancer stem cells, and recruit NuRD, PRC2 and SIN3A to initiate transcriptional repression." (PMID 38028543, 2023). "Moreover, RBBP4 or RBBP7 and BPTF possess high frequency of abnormal copy number in angiosarcoma, breast cancer, pancreatic cancer, prostate cancer and gastric cancer, and are mutated in colorectal adenocarcinoma, lymphoma, melanoma, etc.." (PMID 34736517, 2021). "Due to the involvement of RBBP4/7 in several multi-protein transcription complexes other than ISWI, there has been no exact conclusion as to whether RBBP4 and RBBP7 execute these functions in an ISWI or non-ISWI-dependent manner in breast cancer." (PMID 41278204, 2025).
colon cancer (8 papers, 2021 to 2024). "Aberrant expression of RBBP4 has been implicated in the poor prognosis and metastasis of several highly invasive tumor types, such as colon cancer 21, neuroblastoma 22, and lung cancer." (PMID 39430246, 2024). "Aberrant expression of RBBP4 is implicated in poor prognosis and metastasis of multiple highly metastatic and invasive tumors, including colon cancer 21, neuroblastoma 22, and lung cancer." (PMID 39430246, 2024). "It was shown that RB-binding protein 4 (RBBP4) is associated with a poor prognosis of colon cancer, while our results suggest a favorable effect." (PMID 37895091, 2023). "Interestingly, RBBP4, a downstream regulator of RB1, is upregulated by RB1 mutation and enhances mesenchymal marker expression in human cervical and colon cancer cell lines." (PMID 36230849, 2022). "RBBP4 could promote the malignant progression of colon cancer through the Wnt/β-catenin pathway." (PMID 35814454, 2022). "RBBP4 inhibition reduced cell invasion and migration through the regulation of proteins related to the EMT process in colon cancer, as well as in TNBC cell lines." (PMID 37834160, 2023).
acute myeloid leukemia (6 papers, 2010 to 2025). Acute myeloid leukemia (AML) is a group of neoplasms arising from precursor cells committed to the myeloid cell-line differentiation. "RBBP4 overexpression has been observed in various cancer types, including hepatocellular carcinoma, acute myeloid leukemia, neuroblastoma, breast cancer, thyroid carcinomas, colon cancer, and models of embryonal brain tumors." (PMID 39109577, 2024). "It has been reported that RBBP4 is overexpressed in different human tumors, such as lung, liver and thyroid cancer, acute myelocytic leukemia, and acute lymphoblastic leukemia." (PMID 21114830, 2010). "Previous studies have shown that the RBBP4 protein is overexpressed in various cancers, including hepatocellular carcinoma, 28 colorectal cancer, 29 thyroid cancer, 30 cervical cancer, 31,32 and acute myeloid leukemia." (PMID 40187236, 2025). "RBBP4 is upregulated in acute myeloid leukemia (AML) and is negatively correlated with prognosis." (PMID 38028543, 2023).
lung adenocarcinoma (6 papers, 2021 to 2025). A carcinoma that arises from the lung and is characterized by the presence of malignant glandular epithelial cells. "In conclusion, this study provides new insights into the role of RBBP4 in regulating cisplatin sensitivity, particularly in lung adenocarcinoma and cervical adenocarcinoma models." (PMID 40187236, 2025). "In the present study, the authors found that RBBP4 was overexpressed in human cisplatin-resistant A549/DDP lung adenocarcinoma epithelial and HeLa/DDP cervical cancer cell lines." (PMID 40187236, 2025). "Statistical analysis revealed that RBBP4 expression levels were significantly elevated in lung adenocarcinoma (ADC) compared to lung squamous cell carcinoma (SQC) (p < 0.0001)." (PMID 39109577, 2024). "And the expression of RBBP4 in lung adenocarcinoma with lymphatic metastasis was 2.0077027 times higher than that in a normal one." (PMID 36059662, 2022).